GRAPL-AS1 (GRAPL antisense RNA 1 )
Gene: Long non-coding RNA gene on chromosome 17 (19,062,563 to 19,163,497, reverse strand). Ensembl gene ENSG00000197665.
Gene Ontology:
Biological process: RNA processing
Cellular component: nucleolus